IGF1R (insulin like growth factor 1 receptor)
Diseases named in the same sentence as IGF1R in open-access papers (continued):
Sharing a sentence is not in itself a finding about the gene and the disease.
Stroke (9 papers, 2014 to 2025). Sudden impairment of blood flow to a part of the brain due to occlusion or rupture of an artery to the brain. "In stroke, galectin-3 binds to IGF1R (insulin-like growth factor receptor 1) and TLR4, mediating cytokine release and microgliosis around the infarct site." (PMID 40429840, 2025). "Through intercellular receptor transactivation between CXCR4 and IGF1R signaling pathways, implantation of IGF1R+ MSCs showed significant improvement in neurological function in a stroke model." (PMID 36017096, 2022). "In vivo self-renewal and neuroregenerative potentials of IGF1R+ hDSC were demonstrated in a stroke model." (PMID 27586516, 2016). "In order to demonstrate that interaction of IGF1R+ hDSCs and neural tissue stimulated neurite outgrowth in vivo and in vitro, we quantified neurite regeneration in the stroke rats and an hDSCs/PCCs (primary cortical culture) co-cultured system." (PMID 27586516, 2016). "In stroke-prone SHRs, insulin-like growth factor-1 receptor and its downstream signaling, such as phosphorylated Akt was downregulated." (PMID 25793876, 2015). "To explore the regulatory mechanism of miR-223 in the ischemic pathological process, we also studied the down-stream insulin-like growth factor-1 (IGF-1), IGF1R and IL-6 changes in stroke patients." (PMID 24708646, 2014). "The levels of plasma IGF-1 and IGF1R were greatly increased in the stroke patients group compared to the control group." (PMID 24708646, 2014). "Nevertheless, our study was the first one to suggest the effects of UCW on its potential targets-IGF-1R and VEGF1R, contributing to neuroprotection and thereby preventing the hypoxic-ischemic injury that may be caused by stroke." (PMID 35883879, 2022). "In particular, regarding its neurorestorative effect after stroke, IGF-1R may contribute to improved functional recovery and increased neurogenesis after treatment of stroke in rats with human marrow stromal cells." (PMID 35883879, 2022). "In rat stroke model, animals receiving IGF1R+ hDSCs transplantation, interaction between IGF1R and CXCR4 was demonstrated to promote neuroplasticity, therefore improving neurological function through increasing glucose metabolic activity, enhancing angiogenesis and anti-inflammatiory effects." (PMID 27586516, 2016). "Additionally, enhanced neovascularization and neurogenesis could be the essential mechanisms by which insulin-like growth factor-1 (IGF-1)/IGF-1R improves functional recovery after stroke." (PMID 35883879, 2022). "We also hypothesized that cross-talk between IGF1R and CXCR4 signaling pathways in IGF1R+ hDSC might exert autocrine/paracrine induction of an additive survival signal to enhance neurite regeneration and neuroplasticity in hDSC-transplanted stroke model." (PMID 27586516, 2016). "Moreover, increased IGF-1 and IGF-1R was shown to inhibit inflammatory processes, mainly through inhibiting the expression of proinflammatory cytokines, reducing neurodegeneration and secondary low immune function after stroke." (PMID 27527872, 2016).
thymoma (9 papers, 2015 to 2025). A neoplasm arising from the epithelial cells of the thymus. "Using the thymoma dataset from the TCGA database, we analyzed IGF1R expression in the MG and non‐MG groups and found that IGF1R expression was lower in MG patients and was associated with a poor prognosis (p < 0.05)." (PMID 40152081, 2025). "We analyzed the thymoma dataset from the TCGA database and divided it into two groups to evaluate IGF1R expression in MG patients: patients diagnosed with MG (n = 32) and non‐MG patients (n = 61)." (PMID 40152081, 2025). "In a retrospective analysis, IGF-1R expression was decreased in types A, AB, and B1 thymomas in comparison with types B2, B3, and TC." (PMID 37893096, 2023). "Ten markers, namely Podoplanin, Glut-1, Muc-1, Egfr, Igf1r, c-Jun, and n-Ras, from ten articles that included 748 cases of thymoma and 280 cases of thymic carcinoma were selected." (PMID 32993581, 2020). "Expression of IGF-1R varies between thymomas (4%) and TC (37%), implying different tumor biologies that might be the subject of targeted therapies." (PMID 37893096, 2023). "A phase II study of cixutumumab, an IGF-1R monoclonal antibody, in 49 patients with previously treated advanced thymic tumors showed limited activity in thymoma (ORR 14%, 95% CI 5–29%) and no effectiveness in TC (ORR 0%, 95% CI 0–26%)." (PMID 37893096, 2023).
adrenocortical tumors (8 papers, 2012 to 2025). "Specifically, elevated IGF-2 levels and IGF-1R overexpression has been implicated as a common occurrence related to adrenocortical tumors." (PMID 35457158, 2022). "In present study, we hypothesized that IGF1R overexpression in adrenocortical tumors could be caused by gene amplification, allelic variants, and dysregulated microRNA expression." (PMID 25110710, 2014). "The expression of EGFR and IGF1R were evaluated in a series of adrenocortical tumors by immunohistochemistry." (PMID 27105537, 2016). "We previously demonstrated IGF1R overexpression in 65% of children and 13% of adults with adrenocortical tumors." (PMID 25110710, 2014). "We identified IGF1R overexpression in metastatic pediatric adrenocortical tumors and found that it was a prognostic biomarker of advanced tumors in these children." (PMID 25110710, 2014). "In conclusion, we detected concurrent IGF1R gene copy number variation and IGF1R overexpression in a single functioning malignant adrenocortical tumor." (PMID 25110710, 2014). "As expected, the adrenocortical tumor with IGF1R amplification diagnosed in this patient had higher IGF1R mRNA levels compared to normal adrenal samples." (PMID 25110710, 2014). "Interestingly, this IGF1R upregulation was a predictor of metastases in children with adrenocortical tumors." (PMID 25110710, 2014). "In addition, IGF1R polymorphisms and abnormal microRNA expression did not correlate with IGF1R upregulation in adrenocortical tumors." (PMID 25110710, 2014). "miR-99a-5p and miR-100-5p are downregulated in childhood adrenocortical tumors and repress the proliferation of both adrenocortical tumors and pediatric adrenocortical carcinoma cells by targeting mTOR, RAPTOR, and IGF1R." (PMID 40161350, 2025). "In this study, we firstly evaluated the expression of IGF1R, EGFR and its signaling protein expression in human adrenocortical tumors, then investigated the crosstalk between EGFR and IGF1R pathway, and confirmed the therapeutic effect of co-inhibition of EGFR and IGF1R in ACC." (PMID 27105537, 2016). "miR-126 (median 596.6 (from 30.8 to 2667.4)) was overexpressed in benign and malignant adrenocortical tumors and was not related to IGF1R expression." (PMID 25110710, 2014). "In the microarray data of our series of 140 adrenocortical tumors, the expression of IGF1R in ACC was similar to that in ACA (data not shown)." (PMID 25089899, 2014). "miR-145 (median 2.2 (from 0.01 to 12.6)) had variable expression in the adrenocortical tumors that were evaluated; however, these values were not correlated with the expression values of IGF1R in adrenocortical adenomas and carcinomas." (PMID 25110710, 2014). "Additionally, the amplification of the IGFBP3, FGFR4 (data not shown), and NSD1 (data not shown) genes was also detected in this carcinoma, but IGF1R amplification was not demonstrated in the remaining cases with adrenocortical tumors." (PMID 25110710, 2014).
alveolar rhabdomyosarcoma (8 papers, 2013 to 2023). A rapidly growing malignant mesenchymal neoplasm. "In the translocation-associated Ewing’s sarcoma (EWS), myxoid liposarcomas (MLS) or alveolar rhabdomyosarcoma (ARMS), the fusion proteins EF, FUS-DDIT3 or PAX3-FOXO1, respectively, enhance IGF1R expression, a major driver of RAS/AKT/mTOR activation." (PMID 34294128, 2021).
autism (8 papers, 2017 to 2024). Persistent deficits in social interaction and communication and interaction as well as a markedly restricted repertoire of activity and interest as well as repetitive patterns of behavior. "Further insights were gained through protein-protein interaction analysis, which revealed that IGF1R initially interacts with the protein of autism susceptibility gene YWHAG." (PMID 39376742, 2024). "Differentially expressed autism susceptibility genes after knock out IGF1R and IGF2R in IN-PV cells." (PMID 39376742, 2024). "Conversely, module 8, which includes IGF1R and its co-expressed autism susceptibility genes, showed GO enrichment results indicating that these genes might influence synaptic function and neuronal communication in the neural development by regulating various ion channel functions at the synapse." (PMID 39376742, 2024). "In-depth analysis revealed that IGF1R and IGF2R regulate a group of 182 genes within IN-PV neurons, including 18 genes known to be associated with autism." (PMID 39376742, 2024). "This underscores the significance of the IGF signaling pathway in neurodevelopment and the pathogenesis of autism, as well as the central role of IGF1R within the entire IGF signaling cascade." (PMID 39376742, 2024). "And our findings suggest that targeting the IGF1R could offer new therapeutic strategies for autism, emphasizing the need for further research to unravel the precise molecular mechanisms and interactions at play." (PMID 39376742, 2024). "Finally, HSBP1 and IGF1R were found differentially expressed in autism and, directly or indirectly, modulated by microbiota; namely, HSBP1 is down-regulated after antibiotic administration, and IGF-1 level is affected by gut microbiota composition." (PMID 35405953, 2022). "In conclusion, our study underscores the importance of IGF1R within the IGF signaling pathway and its potential role in the pathogenesis of autism." (PMID 39376742, 2024). "This suggests that disruptions in the structure and function of IGF1R and IGF2R could lead to developmental and functional impairments in IN-PV neurons, potentially contributing to the pathophysiology of autism." (PMID 39376742, 2024). "Notably, recent studies have demonstrated that the conditional knockout of the GIGYF1 gene in mice disrupts IGF1R/ERK signaling pathways, resulting in autism-like behaviors, further supporting our findings." (PMID 39376742, 2024). "Future studies using induced pluripotent stem cell technology to cultivate brain organoids, as well as gene editing techniques in animal models to manipulate IGF1R and related genes, could further elucidate the mechanisms of the IGF signaling pathway in the onset of autism." (PMID 39376742, 2024).
cognitive decline (8 papers, 2010 to 2025). "IGF-1/IGF-1R knockout mice showed decreased brain size, loss of myelination, and cognitive decline, whereas overexpression of IGF-1 resulted in increased brain size and myelination." (PMID 36691085, 2023). "In T2D, insulin resistance and altered IGF-1/IGF-1R signaling are associated with cognitive decline, Aβ production, tau hyperphosphorylation, proinflammatory marker’s expression, oxidative stress, and dyslipidemia." (PMID 36691085, 2023). "Impaired insulin (InsR) and insulin growth factor receptor (IGF-1R) signaling via pAkt/Akt has been linked to cognitive decline in normal aging, as well as AD." (PMID 30631278, 2018). "Another study has reported that increased hippocampal IGF-1R mRNA expression was associated with aging and cognitive decline, suggesting that upregulation of IGF-1R mRNA levels may be part of the degenerative atrophy response to the hippocampal formation during aging." (PMID 36615827, 2022). "These high-risk genes dysregulated in more than one cell type, such as IGF1R, DDIT4, and CST3, may be potential targets for delaying the onset of cognitive decline and neurodegenerative diseases in the elderly." (PMID 40036868, 2025). "The relationships between the observed correlations of diet and the CSF1R, IGF1R, and PINK1 expression with regard to cognitive decline are less clear." (PMID 36771351, 2023).
developmental delay (8 papers, 2008 to 2025). "Insulin-like growth factor-1 receptor (IGF1) gene haploinsufficiency on chromosome 15q26.3 is linked to reduced prenatal and postnatal growth, developmental delay, dysmorphic features, and skeletal abnormalities." (PMID 38591204, 2024). "IGF1R contributes to a wide range of developmental processes such as development of the central nervous and cardiovascular systems, and monozygosity for this gene could contribute to the developmental delay and complex cardiac defects seen in our patient." (PMID 18194513, 2008). "The most predictive factors for IGF-1R deletion include small birth size, head size, and stature, as well as high IGF-1 levels, developmental delay, and micrognathia." (PMID 22587301, 2012). "PLAG1, HMGA2, and IGF1R patients exhibited a lower frequency of body asymmetry and of relative macrocephaly at birth and postnatal life, while IGF2 patients displayed an increased frequency of feeding difficulties, heart defects, skeletal malformations, and developmental delay." (PMID 39412159, 2025). "A combination of direct effects (due to lack of IGF-1R in lung tissue) and indirect effects (secondary to marked muscle hypoplasia) could explain the exceptionally strong developmental delay observed in IGF-1R−/− lungs." (PMID 23139760, 2012). "She scored ≥ 3 on the IGF1R clinical score but had syndromic features not typical of insulin-like growth factor 1 receptor (IGF1R) defects, including triangular face, high-pitched voice, high-arched palate, and developmental delay (inattention and poor motor, writing, and reading skills)." (PMID 38888172, 2024).
diabetic cardiomyopathy (8 papers, 2017 to 2025). Diabetic cardiomyopathy is a disorder of the heart muscle in people with diabetes. "This microRNA downregulates HSP60, a regulator of insulin-like growth factor-1 receptor (IGF-1R) signaling, which is inversely associated with the progression of diabetic cardiomyopathy." (PMID 40001534, 2025). "IGF-1/IGF-1R axis has been proposed as a therapeutic candidate against the pathophysiological progress of diabetic cardiomyopathy (DCM)." (PMID 37851320, 2023). "Overexpression of decorin ameliorated diabetic cardiomyopathy and promoted angiogenesis through the IGF1R-Akt-VEGF signaling pathway in endothelial cells in vivo and in vitro." (PMID 32731559, 2020). "In conclusion, overexpression of decorin ameliorated diabetic cardiomyopathy and promoted angiogenesis through the IGF1R-AKT-VEGF signaling pathway in vivo and in vitro." (PMID 28290552, 2017).
diffuse large B-cell lymphoma (8 papers, 2017 to 2025). "Moreover, the insulin‐like growth factor‐1 receptor (IGF‐1R) is involved in the regulation of Hippo–YAP signaling in diffuse large B‐cell lymphoma (DLBCL) tumorigenesis." (PMID 37799806, 2023). "In diffuse large B-cell lymphoma, IGF1R blockade using AG1024 or PPP or short hairpin RNA decreased the expression of the oncogenic YAP protein and enhanced MST1 expression, suggesting that the IGF1R might contribute in regulating the Hippo pathway." (PMID 34440844, 2021). "The regulation of YAP by IGF-1R signaling was reported in diffuse large B-cell lymphoma (DLBCL) and sorafenib-resistant HCC." (PMID 37081542, 2023). "The latest study has indicated that SMO is involved in the regulation of the oncogenic IGF1R/AKT signaling axis and is unrelated to canonical Hedgehog signaling in diffuse large B-cell lymphoma (DLBCL)." (PMID 36405701, 2022).
fibrosis (8 papers, 2011 to 2025). the formation of excess fibrous connective tissue in an organ or tissue in a reparative or reactive process. "Indeed, Yamaguchi and colleagues, using an animal model of chronic heart failure, demonstrated that RIC treatment induced recruitment of the exosome rich in miR-29a and insulin-like growth factor 1 receptor (IGF-1R), both biomolecules with protective roles against cardiac fibrosis and remodeling." (PMID 33198302, 2020).
growth deficiency (8 papers, 2014 to 2022). "IGF1R plays a pivotal role in cell survival by regulating somatic growth, development, and metabolism, as demonstrated by using IGF1R knock-out mice that displayed severe growth deficiency, lethal neonatal lung hypoplasia, and muscle hypoplasia." (PMID 32911852, 2020). "On the other hand, some children with heterozygous mutations of IGF1R exhibit intrauterine growth retardation although this phenotype has variable penetrance even for children with the same mutation." (PMID 29644076, 2018). "Loss of IGF-1R leads to severe growth deficiency and developmental delays in ossification." (PMID 32754602, 2020).
Hepatic steatosis (8 papers, 2015 to 2025). Steatosis is a term used to denote lipid accumulation within hepatocytes. "This study examines how IR and IGF1R signaling impact hepatic and systemic metabolism and contribute to the spontaneous development and progression of hepatic steatosis and tumors driven by PTEN deficiency." (PMID 40115165, 2025). "The deletion of the miR379 cluster attenuates hepatic steatosis and metabolic dysfunction of leptin-receptor-deficient type 2 mice induced by a high-fat diet, and the insulin-like growth factor 1 receptor is directly targeted by miR379." (PMID 38282657, 2024). "Therefore, IR deficiency led to a decrease in hepatic lipid synthesis, resulting in less hepatic steatosis, whereas IGF1R deficiency increased lipid oxidation and ketogenesis under fed conditions." (PMID 40115165, 2025). "Taken together, these results show an effect of DPP-4 inhibition on hepatic steatosis that is induced by the acute inhibition of IR/IGF1R signaling through an insulin signaling-independent pathway." (PMID 33105604, 2020). "In this study, we reported that the DPP-4 inhibitor linagliptin ameliorated hepatic steatosis elicited by the dual IR/IGF1R inhibitor OSI-906." (PMID 33105604, 2020). "OSI-906 administration induces the acute inhibition of IR/IGF1R signaling and evokes hepatic steatosis." (PMID 33105604, 2020). "Preclinical studies show that IGF-1R activation suppresses HIF-1 signaling, reducing metabolic dysfunction, hepatic steatosis, and inflammation in high-fat diet-fed mice." (PMID 40600138, 2025). "In summary, in hepatic steatosis and HCC, PTEN expression is reduced/lost, whereas signaling through IR and IGF1R is elevated." (PMID 40115165, 2025). "In contrast, IGF1R deletion did not reduce hepatic steatosis." (PMID 40115165, 2025). "Hence, the effect of linagliptin on hepatic steatosis seemed to be independent of the IR/IGF1R signaling pathway." (PMID 33105604, 2020).
Hypoglycemia (8 papers, 2013 to 2025). A decreased concentration of glucose in the blood. "Hypoglycemia is further exacerbated by IGF-2 binding to IGF-1R and IR at the pancreatic alpha cells and hypothalamus, which mimics the effects of insulin and IGF-1 to suppress secretion of counterregulatory hormones—glucagon and GH." (PMID 41179270, 2025). "An IHC study on three SFTs with hypoglycemia revealed marked staining for IGF-1R." (PMID 24944670, 2014).
Infertility (8 papers, 2015 to 2025). "Mice with inactivation of IGF1R in granulosa cells are rendered infertile due to the stagnation of follicular development in the pre-ovulatory phase." (PMID 40076037, 2025). "These mice exhibited subfertility in Igf1r mutants and complete infertility in Insr/Igf1r double mutants (DKO)." (PMID 38790245, 2024). "The Stocco group conditionally ablated Igf1r using a combination of Esr2-Cre and Cyp19-Cre and found female mice were infertile due to a block in antral follicle formation leading to ovulation failure." (PMID 38790245, 2024). "Normalization of stromal proteins expression of IGF-1R and LEP in obese mice ovaries may be essential for reversion of androgenic medium, hormonal equilibrium, in the body weight regulation and the glycose metabolism, and, therefore, the regulation of obese/infertility phenotype of this model." (PMID 29430464, 2017).